WRN (WRN RecQ like helicase)
Diseases named in the same sentence as WRN in open-access papers (continued):
Sharing a sentence is not in itself a finding about the gene and the disease.
colon carcinoma (8 papers, 2011 to 2025). "Since colon carcinoma is an age-associated disease, we further analyzed WRN expression in human colon carcinoma." (PMID 40261911, 2025). "Colon cancer samples with somatic variants in WRN were more likely to be from right-sided cancers and were associated with increased tumor mutation burden and microsatellite instability (MSI)." (PMID 35782872, 2022). "In addition, WRN-mutated colon cancer has a characteristic immunologic profile with higher PD-L1 expression in contrast to WRN wildtype which could impact response to immunotherapy." (PMID 35782872, 2022). "A targeted gene sequencing test (next-generation sequencing (NGS)) for 88 genes related to colon cancer found mutations in two different genes: the PMS2 (p.Arg20Gln) and the WRN (p.Leu628Val) genes (for more information)." (PMID 25018888, 2014). "They found that the overall survival of patients was 39.4 months for patients with WRN methylated but only 20.7 months for WRN unmethylated colon tumors." (PMID 24359226, 2013). "RT-qPCR analyses confirmed that WRN expression was elevated in colon carcinoma tissues." (PMID 40261911, 2025).
ovarian carcinoma (7 papers, 2016 to 2024). A malignant neoplasm originating from the surface ovarian epithelium. "For this, we compared the relative viability of BRCA2-mutated ovarian cancer cell line PEO1 with that of BRCA2 WT revertant PEO4 cells upon WRN helicase inhibition." (PMID 34772932, 2021). "Human DNA helicases RECQL1 and WRN proteins have been reported as therapeutic targets for several cancers, including ovarian cancers." (PMID 33525614, 2021). "WRN encodes a DNA helicase and nuclease that functions in DNA replication, repair, and transcription and has recently been identified as a SL vulnerability of MMR-deficient MSI cancers, including some colorectal, endometrial, gastric, and ovarian cancers." (PMID 39578878, 2024). "Having demonstrated that WRN complementation partially rescued the hyper-degradation phenotype of BRCA2-depleted cells, we tested the effect of WRN knockdown on nascent DNA degradation in the BRCA2-mutated ovarian cancer cell line PEO137." (PMID 34772932, 2021). "Similarly, we found that in a BRCA1-deficient background of an ovarian cancer cell line, depleting WRN does not suppress upregulated resection, indicating that WRN is not involved in it (Sidorova, unpublished)." (PMID 29355244, 2017).
gastric cancer (6 papers, 2013 to 2025). A primary or metastatic malignant neoplasm involving the stomach. "By studying colonic and gastric cancer cells, two recent studies have shown that WRN is upregulated in cancers with microsatellite instability (MSI) and is essential for survival in these cancers." (PMID 40261911, 2025). "SULF2 and WRN promoter methylation detection indicates potential predictive biomarkers to identify and target the most sensitive gastric cancer subpopulation for personalized CPT-11 therapy." (PMID 24359226, 2013). "The properties of stem cells in gastric cancer are regulated by WRN." (PMID 37626815, 2023). "What makes the case even more interesting is that gastric cancer appearing with both SULF2 and WRN methylation is remarkably more sensitive with CPT-11." (PMID 24359226, 2013). "At present, no study has compared the correlation between SULF2, WRN promoter methylation and clinicopathological parameters of patients with gastric cancer and the sensitivity to irinotecan (CPT-11)." (PMID 24359226, 2013). "However, up to now, the correlation between SULF2, WRN promoter methylation and the chemosensitivity of irinotecan in gastric cancer has not been studied yet." (PMID 24359226, 2013).
osteoporosis (6 papers, 2011 to 2025). A condition of reduced bone mass, with decreased cortical thickness and a decrease in the number and size of the trabeculae of cancellous bone (but normal chemical composition), resulting in increased fracture incidence. "Besides WS, nonsynonymous SNPs in the WRN gene were associated with physiological traits and age‐related diseases, including short stature, head circumference in infant, cardiovascular disease, dyslipidemia, diabetes, osteoporosis, and ocular cataracts." (PMID 40530580, 2025). "Former study showed that mutational inactivation of the gene WRN and gene TERC (encoding the telomerase RNA component) would lead to telomere dysfunction and cause osteoporosis with low cortical bone mineral density." (PMID 31754224, 2019).
Fanconi anemia (5 papers, 2014 to 2025). Fanconi anemia (FA) is a hereditary DNA repair disorder characterized by progressive pancytopenia with bone marrow failure, variable congenital malformations and predisposition to develop hematological or solid tumors. "For example, VC treatment led to the reactivation of the DNA replication pathway that was repressed in WRN-deficient MSCs, and of the various DNA repair pathways including mismatch repair, homologous recombination, base excision repair, and Fanconi anemia pathway." (PMID 27271327, 2016). "Moreover, 14% of the patients included in this study harbored deleterious mutations in Fanconi anemia genes (FANCA, FANCD2, FANCF, FANCG FANCI and FANCL) and in WRN, which have been reported to interact with BRCA1." (PMID 38184614, 2024).
lipodystrophy (5 papers, 2013 to 2026). A congenital or acquired disorder characterized by abnormal loss or redistribution of the adipose tissue in the body. "Whether WRN-linked lipodystrophy could be secondary to primary mesenchymal cellular senescence, as it was suggested in laminopathies, needs to be further investigated." (PMID 23849162, 2013). "The pathophysiological link between partial lipodystrophy and cellular senescence has been previously evoked not only for LMNA mutations but also with the description of lipodystrophy syndrome resulting from mutations in WRN which encodes the DNA helicase WRN, involved in DNA replication and repair." (PMID 27120622, 2016).
non-small cell lung carcinoma (5 papers, 2010 to 2024). A group of at least three distinct histological types of lung cancer, including non-small cell squamous cell carcinoma, adenocarcinoma, and large cell carcinoma. "Recent studies showed that conditional gene silencing of WRN expression in non-small-cell lung cancer xenografts that are over-expressed with c-MYC inhibits tumor growth, suggesting that targeting WRN protein inhibits growth of c-MYC-associated cancers." (PMID 25620975, 2014). "Grandori and coworkers also addressed the role of WRN in Myc associated cancer in xenografts experiments using a non-small cell lung carcinoma cell line expressing high levels of Myc (A549, NSCLC) where WRN was silenced by RNA knock-down." (PMID 22373487, 2012). "WRN has been reported to undergo epigenetic inactivation through CpG island promoter hypermethylation in about one-third of non-small cell lung cancer." (PMID 21151896, 2010). "Importantly, WRN depletion impaired tumor growth in c-Myc-driven non-small cell lung cancer xenografts and Eμ-Myc-driven B-cell lymphoma in a mouse model, suggesting that WRN upregulation by c-Myc promotes tumorigenesis." (PMID 39456601, 2024).
prostate carcinoma (5 papers, 2021 to 2025). A carcinoma that arises from epithelial cells of the prostate gland. "In prostate cancer, the single nucleotide polymorphism of WRN Leu1074Phe was associated with the risk of prostate cancer in Chinese men, and the TG/GG genotype displayed a decreased prevalence of prostate cancer compared with the TT genotype." (PMID 40649870, 2025). "In BRCA2-deficient cells, including prostate cancer, WRN is preferentially localized on the replication fork." (PMID 40649870, 2025). "WRN G327X mutations create a premature translational stop signal and can cause a category of pathogenicin hereditary prostate cancers." (PMID 40649870, 2025). "In previous studies, we reported a series of WRN inhibitors with good anti-prostate cancer activity in vivo and in vitro, but the molecular mechanisms are still unclear." (PMID 40649870, 2025). "In our previous study, we found a quinazoline compound kzl052, which has a WRN-dependent inhibitory effect on prostate cancer cells, but its molecular mechanism needs to be further explored." (PMID 40649870, 2025). "This study aimed to explore the molecular mechanism of the quinazoline analog kzl052 targeting WRN against prostate cancer and provide a theoretical basis and treatment strategy for targeting WRN helicase in the treatment of prostate cancer." (PMID 40649870, 2025). "In this study, we found that kzl052, a novel WRN inhibitor, significantly inhibited the progression of prostate cancer in vitro and in vivo by regulating replication fork stability." (PMID 40649870, 2025). "It has become one of the hot targets of genotoxic drugs, but the effect and mechanism of targeting WRN against prostate cancer is still unclear." (PMID 40649870, 2025). "The Western blotting results showed that the WRN protein was expressed differently in various prostate cancer cell lines and was highly expressed in 22RV1 and PC3 cells." (PMID 40649870, 2025). "Therefore, targeted inhibition of WRN helicase may be beneficial for the treatment of some prostate cancer patients." (PMID 40649870, 2025).
type 2 diabetes mellitus (5 papers, 2014 to 2025). A type of diabetes mellitus that is characterized by insulin resistance or desensitization and increased blood glucose levels. "Previous studies have reported associations between WRN polymorphisms and age-related diseases such as myocardial infarction and type 2 diabetes mellitus." (PMID 29689049, 2018).
cataract (4 papers, 2013 to 2022). Partial or complete opacity of the crystalline lens of one or both eyes that decreases visual acuity and eventually results in blindness. "Cataracts are one of the most commonfeatures observed in patients with WS.WRN expression is severely affectedby promoter hypermethylation in age-related cataract lens cells." (PMID 29043077, 2017).
glioblastoma (4 papers, 2016 to 2025). The most malignant astrocytic tumor (WHO grade IV). "Alternatively, since WRN helicase plays an essential role in MMR-deficient cells, treatment with a WRN inhibitor might eliminate the emerging TMZ-resistant MMR-deficient glioblastoma cells." (PMID 39011394, 2024).
meningioma (4 papers, 2011 to 2025). A generally slow growing tumor attached to the dura mater. "Meningioma frequently occurs in WS patients, and this is likely a consequence of a reduced WRN expression due to the elevated methylation of the WRN promoter." (PMID 33718381, 2021).
soft tissue sarcoma (4 papers, 2011 to 2025). A malignant neoplasm arising from muscle tissue, adipose tissue, blood vessels, fibrous tissue, or other supportive tissues excluding the bones. "This is supported by recent studies that showed association between WRN polymorphism and risks of cancer development, including, but not limited to breast, gastric adenocarcinoma and bone and soft tissue sarcomas." (PMID 21267443, 2011). "The polymorphisms of WRN gene is associated with increased risks of cancer development, including but not limit to breast, gastric adenocarcinoma and bone and soft tissue sarcomas." (PMID 21267443, 2011).
thyroid cancer (4 papers, 2011 to 2026). "Of relevance to this work, a clinical study reported that different mutations in the WRN protein were associated with different subtypes of thyroid carcinomas in Japenese patients with WS." (PMID 26447695, 2015).
xeroderma pigmentosum (4 papers, 2014 to 2022). Xeroderma pigmentosum (XP) is a rare genodermatosis characterized by extreme sensitivity to ultraviolet (UV)-induced changes in the skin and eyes, and multiple skin cancers. "For example, BLM, WRN, and RECQL4 are mutated in Bloom, Werner, and Rothmund-Thomson genomic instability syndromes, respectively, and XPB and XPD are mutated in Xeroderma Pigmentosum, characterized by high risk of skin cancer." (PMID 25238049, 2014). "Only BRCC3 (p-value log(−10) = 1.87), WRN (p-value log(−10) = 2.09), USP45 (p-value log(−10) = 1.52) and the xeroderma pigmentosum complementation group A (XPA; p-value log(−10) = 1.32) were significantly upregulated." (PMID 36010871, 2022).
anemia (3 papers, 2016 to 2020). A reduction in the number of red blood cells, the amount of hemoglobin, and/or the volume of packed red blood cells. "Thus, similar to a recent report analyzing Fanconi anemia complementation group I (FANCI), ATR-mediated WRN phosphorylation is somehow involved in the suppression of dormant origin firing upon replication stress." (PMID 26695548, 2016).
atherosclerosis (3 papers, 2008 to 2022). A disease characterized by the build-up of fatty material and calcium deposition in the arterial wall resulting in partial or complete occlusion of the arterial lumen. "One of the first evidences that links WRN to the atherosclerosis process during normal aging involves the well known WRN polymorphisms: C1367R (refSNP ID: rs1346044) and L1074F (refSNP ID: rs2725362)." (PMID 18312663, 2008). "Therefore, we hypothesize that WRN protein could be relevant for the regulation of the atherosclerosis process, even in humans without WS." (PMID 18312663, 2008).
colorectal tumor (3 papers, 2012 to 2021). "The functional assessments indicated that the damaging effects on WRN gene products were attributed to genomic instability in colorectal tumor cells." (PMID 34164337, 2021). "We tested 51 patient colorectal tumor and normal tissue extracts for expression of the RecQ-family helicase WRN because it is known to act preferentially on aberrant structures such as triplexes and G-quadruplexes and to promote genomic integrity." (PMID 22682314, 2012).
endometrial cancer (3 papers, 2019 to 2021). Primary or metastatic malignant neoplasm involving the endometrium (mucous membrane that lines the endometrial cavity). "WRN inactivation is selectively associated with the MSI-H status of cancer cells rather than the microsatellite stable (MSS) status of colorectal and endometrial cancer cell lines." (PMID 34943966, 2021). "WRN mRNA levels were similarly reduced upon transfection of pooled or individual WRN-targeting siRNAs in all four endometrial carcinoma models." (PMID 30910006, 2019). "Loss of WRN selectively impairs viability of MSI-H CRC and endometrial cancer cell models." (PMID 30910006, 2019). "Depletion of WRN exclusively affects viability of a subset of CRC, gastric and endometrial cancer cell models reflected by RSA (redundant siRNA activity) sensitivity scores ≤−3, indicative of cell essentiality." (PMID 30910006, 2019). "Likewise, we observed that WRN knock-down impaired viability of three MSI-H endometrial carcinoma cells lines (HEC-265, ISHIKAWA, HEC-6), but not the MSS cell line MFE-280." (PMID 30910006, 2019). "We demonstrate that WRN inactivation selectively impairs the viability of MSI-H but not microsatellite stable (MSS) colorectal and endometrial cancer cell lines." (PMID 30910006, 2019).
hereditary cancer (3 papers, 2020 to 2023). Malignant neoplasms occurring in families at a rate greater than that expected by chance and caused by germline mutations in a specific gene. "More importantly, various evaluations have suggested a crucial role for WRN associated with different types of familial cancers, specifically breast and ovarian cancers." (PMID 34164337, 2021). "Nevertheless, the potential role of WRN in CRCs remains elucidated, and further studies are needed to reveal its role in hereditary cancers, HNPCC subtypes in particular." (PMID 34164337, 2021). "In addition to mutations associated with risk of hereditary cancer, pathogenic/likely pathogenic mutations were detected in ERCC2 (n = 1), FANCA (n = 1), FANCC (n = 1), HNF1A (n = 1), PRF1 (n = 1) RECQL4 (n = 2), WRN (n = 1), and XPA (n = 1)." (PMID 31963545, 2020). "Notably, epigenetic inactivation of the WRN gene was introduced as a common event in sporadic colorectal tumorigenesis as described for other DNA repair tumor suppressor genes, hMLH1 and BRCA1, involved in hereditary cancers." (PMID 34164337, 2021).
laminopathies (3 papers, 2010 to 2018). "Our present results show that fibroblasts with WRN null mutations present nuclear deformations similar to those observed in laminopathies, as described in one previous study." (PMID 23849162, 2013). "On the other hand, the phenotypes generated by mutations affecting genes directly acting on DNA function, as mutations in the helicases WRN and BLM or in the polymerase polδ, share many of the traits of progeroid laminopathies." (PMID 29936894, 2018).
leukemia (3 papers, 2016 to 2025). A malignant (clonal) hematologic disorder, involving hematopoietic stem cells and characterized by the presence of primitive or atypical myeloid or lymphoid cells in the bone marrow and the blood. "This is notable since leukemia cell lines from the NCI60 tumor cell line panel show higher-than-average drug sensitivity to both previously published WRN inhibitors: NSC 617145 and NSC 19630." (PMID 30625228, 2019). "Recent evidence shows that treatment with the WRN inhibitor NSC 19630 significantly affects the cellular growth of different leukemia cell lines." (PMID 27829440, 2016). "Interestingly, evidence shows that treatment with a WRN inhibitor (NSC 19630) significantly affects cellular proliferation of leukemia cell lines." (PMID 27829440, 2016). "Targeted inhibition of the WRN helicase induced cell cycle arrest and apoptosis in HTLV-1-transformed leukemia cells." (PMID 27829440, 2016). "DNA repair inhibitors induced cell death in different human leukemias, and in the absence of an effective treatment for ATLL, we decided to test the cytotoxicity of a WRN helicase inhibitor." (PMID 27829440, 2016).
Li-Fraumeni syndrome (3 papers, 2011 to 2021).
pancreatic cancer (3 papers, 2023 to 2025). "Lower OS is linked to increased expression of RECQL, BLM, and WRN in pancreatic cancer." (PMID 37626815, 2023). "Pancreatic cancer showed an exceptionally high biallelic loss in HRR genes, with BRCA1, CDK12, FANCC, PPP2R2 A, RAD51 C, RAD51D, RAD52, WRN, and XRCC3 all presenting 100% biallelic loss." (PMID 40420266, 2025). "Three germline deleterious variations in cancer susceptibility genes, known as pancreatic cancer susceptibility genes (ATM, WRN, and PALB2), were identified in our study population." (PMID 37313463, 2023).
chronic myelogenous leukemia (2 papers, 2013 to 2019). "WRN has been found to be upregulated in chronic myeloid leukemia, allowing for increased cell survival through an alternative nonhomologous end-joining pathway." (PMID 30625228, 2019). "The Werner syndrome helicase (WRN), together with LIG3, was found upregulated in chronic myelogenous leukemia (CML), where several D-NHEJ activities are suppressed." (PMID 23675572, 2013).